SPP1 (secreted phosphoprotein 1)
Diseases named in the same sentence as SPP1 in open-access papers (continued):
Sharing a sentence is not in itself a finding about the gene and the disease.
tumor (continued). "Similarly, we further performed correlation analysis of SPP1 expression with these immune checkpoint genes based on different stages and grades of the tumor." (PMID 35067176, 2022). "Taken together, these findings indicated that SPP1 expression significantly correlated with tumor immune microenvironment and may promote tumor immune tolerance process." (PMID 36585688, 2022). "Notably, the SPP1 signal is turned on in tumor tissue, and the accumulated effect strength of it in the tumor is obviously higher than other pathways." (PMID 35812372, 2022). "In order to investigate the SPP1 expression differences in tumor and normal samples of cancers." (PMID 35067176, 2022). "The expression of SPP1 was significant related to prognosis, tumor mutation burden (TMB), microsatellite instability (MSI), and immune checkpoint genes, suggested that SPP1 plays an essential role in the tumor immune microenvironment and immune cell infiltration." (PMID 35067176, 2022). "The decreased mRNA levels of SPP1 after DPT treatment may suggest a role of DPT in reducing tumour progression." (PMID 36012487, 2022). "Therefore, we calculated the relative abundance of 22 types of immune cells in each tumor, and analyzed their correlation with SPP1 expression." (PMID 35067176, 2022). "Also, SPP1+TAMs, potentially enhancing tumor metastasis and immunosuppression, are observed to be highly expanded in hypoxia TME across independent patient samples in six cancer types." (PMID 35281061, 2022). "Then we found the interesting information that serum level of anti-SPP1 autoantibody was significantly higher in ESCC patients with family tumor history, which could distinguish ESCC patients with family tumor history from that without family tumor history." (PMID 36038839, 2022). "The relative expression level of SPP1 was significantly lower in stage I tumor tissues." (PMID 34977039, 2021). "SPP1 released by tumor cells increased TAM infiltration and immunosuppression." (PMID 33766119, 2021). "We then sought to elucidate whether SPP1 expression was driven by expansion of a subset of myeloid cells, such as myeloid-derived suppressor cells, with high expression of SPP1 at baseline, or was due to a tumor-resident state." (PMID 33670921, 2021). "In addition, we found that the SPP1/CD44 signaling plays important roles in the induction of MES-like tumor cells." (PMID 34805184, 2021). "Levels of PRKCD and SPP1 also varied among different clinical stages and tumor grades." (PMID 34631695, 2021). "At present, the roles of CXCL13, IDO1 and SPP1 in immune process of tumor have been studied." (PMID 34736480, 2021). "SPP1 has a role in tumor progression, in metastasis in BC, and in recurrence in ER-positive BC." (PMID 34298771, 2021). "We found that the methylation level of the SPP1 promoter region in tumor tissues was significantly lower than that in normal tissues, which might contribute to the high expression of SPP1 in tumor tissues." (PMID 33996808, 2021). "The expression of SPP1 is positively related to tumor grading." (PMID 34977258, 2021). "SPP1 promotes tumorigenesis and metastasis through accumulation of vascular endothelial growth factor (VEGF) and facilitates immune escape from tumors through upregulation of PD-L1 tumor-associated macrophages." (PMID 34671675, 2021). "Secreted Phosphoprotein 1 (SPP1) gene encodes for Osteopontin (OPN), a sialic acid rich, chemokine-like, matricellular phosphoglycoprotein, with well-defined roles in cell-matrix interaction, inflammatory responses, angiogenesis, and tumor metastasis." (PMID 34195201, 2021).
tumor (continued). "We further evaluated the differences in the tumor-infiltrating immune cells (TICs) in the immune microenvironment between groups with different levels of SPP1 expression, and those with or without EGFR mutation." (PMID 34178613, 2021). "Compared to macrophages in the normal tissues, the TAMs have high expression of APOE (Fold change = 23.65909118, adjusted p value = 2.225074e−308) and SPP1 (Fold change = 17.40700342, adjusted p value = 2.225074e−308), which were reported to promote tumor cell growth and invasiveness." (PMID 33144684, 2021). "Secreted phosphoprotein 1 (SPP1), a hallmark gene of the EMT process, can participate in extracellular matrix (ECM)-receptor interactions and the focal adhesion response pathway to regulate tumor metastasis and invasion." (PMID 34646827, 2021). "Evidently, SPP1 generated by NSCLC tumor cells could polarize TAMs to M2-like phenotypes and induce the synthesis of VEGF, thereby promoting tumor progression." (PMID 34804043, 2021). "The high expression of SPP1 was also correlated with tumor grade and poor clinical prognosis." (PMID 33996808, 2021). "Finally, the correlations between macrophages and lymph node metastasis and SPP1 expression were validated through the IHC analysis of tumor samples." (PMID 34646827, 2021). "DKK3 may function as a tumor suppressor gene, and SPP1 functions as a cytokine resulting in increased interferon-gamma and interleukin-12 expression, and has been associated with enhanced tumor cell invasion and dissemination in EAC." (PMID 34638363, 2021). "Further, we showed that SPP1 overexpression in A549 cells promoted xenograft tumor growth in mice." (PMID 33996808, 2021). "Moreover, hypoxia, in the current study, is disclosed to be a factor to influence the intercellular crosstalk, metabolic reprogramming, tumor heterogeneity, SPP1+ TAM expansion, and T cell exhaustion, thus promoting cancer development." (PMID 34676217, 2021). "Interestingly, when tumor growth was compared between these experimental groups, SPP1 knockdown tumors grew better in immunodeficient compared to immunocompetent mice." (PMID 34832904, 2021). "In addition, the strong correlation between SPP1 and marker genes of immunity indicates the contribution of SPP1 for tumor immunology in HNSCC." (PMID 34977258, 2021). "Further analyses showed that SPP1 significantly contributed to tumor differentiation." (PMID 34977258, 2021). "SPP1 is a key factor that mediates the polarization process of macrophages, and could provide new ideas for tumor immunotherapy strategies." (PMID 32815653, 2020). "In this work, 4 selected cancer databases were mined, which suggested that SPP1-correlated common genes and miRNAs may be involved in tumor immune infiltration, cancer progression and metastasis in COAD, HNSC, LUAD, and LUSC." (PMID 33324676, 2020). "Besides regulating bone mineralization, SPP1 has also been shown playing a role in tumor cell proliferation, adhesion, invasion and metastasis." (PMID 33240930, 2020). "In PTEN-deficient tumor models, enhanced LOX production is responsible for the enhanced attraction of macrophages via the β1 integrin-PYK2 pathway, which subsequently promote tumor growth via SPP1." (PMID 32014107, 2020). "It indicated that the COL1A1, IGF1, COL5A1, CXCL12, PTEN, and SPP1 were significantly differently expressed in EC tumor compared with those in normal samples (P = 4.93E−02, P = 5.24E−03, P = 2.83E−04, P = 1.58E−06, P = 2.11E−12, and P = 6.91E−13, respectively)." (PMID 32641130, 2020). "This further confirmed that SPP1 might promote tumor progress through interacting with common genes and facilitating immune cell infiltration in these cancers." (PMID 33324676, 2020). "Upon activation, we observed altered transcription of KITLG, TGFB1, IFNG, SPP1, IL17A and PDCD1, whose associated functions and expression pattern marked and improved OS of BrC patients, supporting that MCs contribute with a tumor stroma with anti-tumoral functions in BrC." (PMID 32722549, 2020).
tumor (continued). "M2 macrophages tumor infiltration was positively correlated with SPP1 in four selected cancers." (PMID 33324676, 2020). "Unfortunately, in this study, we failed to obtain SPP1 splice variants data to further investigate their relationship with tumor-associated genes and immune infiltration." (PMID 33324676, 2020). "Additionally, we detected OCT4 and SPP1 transcripts at high frequencies in tumours with invasive regions (gene score: ≥2.0; 15/17)." (PMID 32503462, 2020). "CD44 antigen is a receptor for hyaluronic acid and can interact with SPP1 and other ligands, allowing it to participate in a wide variety of cellular functions, including lymphocyte activation, recirculation and homing, hematopoiesis, and tumor metastasis." (PMID 33375642, 2020). "However, a higher degree of tumour dedifferentiation in WT compared to Spp1−/− animals was shown in histologic analyses, as indicated by a significantly higher tumour grade in livers of wild‐type mice." (PMID 32281248, 2020). "The correlation between osteomimicry and tumor purity was then investigated, and result showed that SPARC and SPP1 expression had a moderate-to-strong and positive correlation with tumor purity, while BGLAP expression had a poor-to-moderate and negative correlation with tumor purity." (PMID 33240930, 2020). "Furthermore, lung adenocarcinoma cells secrete phosphoprotein 1 (SPP1) to induce the expression of PD-L1 in M2 macrophages and enhance the M2-polarized effect of macrophages, thus promoting tumor progression." (PMID 33224886, 2020). "Therefore, it is reasonable to believe that SPP1 promotes tumor progression by interacting with the receptor in COAD, HNSC, LUAD, and LUSC." (PMID 33324676, 2020). "M0 macrophages tumor infiltration was positively correlated with SPP1 in COAD, HNSC, and LUAD." (PMID 33324676, 2020). "Whether these SNPs affect the progression of DMD remains unknown, although SPP1, also known as osteopontin, is a cytokine that regulates inflammation, tissue remodeling, cellular immunity, and tumor cell metastasis in many pathologies and disorders." (PMID 32849198, 2020). "The relative expression of COL1A1, IGF1, COL5A1, CXCL12, and PTEN in tumor samples was significantly lower compared to those in adjacent normal samples (P < 0.05), while SPP1 expression was significantly higher in tumor samples compared to the adjacent normal samples (P < 0.05)." (PMID 32641130, 2020). "All of these data provide strong evidence that SPP1 may promote tumor progress through interacting with carcinogenic genes and facilitating immune cells’ infiltration in COAD, HNSC, LUAD, and LUSC." (PMID 33324676, 2020). "COL10A1 and SPP1 were upregulated in tumor tissues, and SGCG was downregulated." (PMID 33324550, 2020). "To examine whether the OCT4/SPP1 axis can help identify patients with early-stage LUAD at high-risk of metastasis, we investigated primary tumours of early-stage (Stage I) LUAD patients, which were collected from surgical patients at Okayama University." (PMID 32503462, 2020). "The expression level of SPP1 correlates with tumor stage and aggressiveness, suggesting that OPN may be a diagnostic and prognostic biomarker for several cancers." (PMID 31849319, 2019). "This indicates that SPP1 is a tumor-promoting gene in these cancers." (PMID 31849319, 2019). "These showed that the stretch of DNA sequence containing the rs28357094 SNP is not only needed in tumor cell lines to maintain high levels of SPP1 expression, probably through Sp1 transcription factor binding, but it also includes a non-palindromic glucocorticoid receptor responsive element (GRE)." (PMID 31083420, 2019). "Similarly, SPP1 was also found to be increased in normal human breast tissue at a high risk of developing BRC and promote inflammation and tumor growth by reprograming normal mammary fibroblasts." (PMID 31921672, 2019).
tumor (continued). "With regard to the composition of WHF from the surgery bed following the removal of various molecular subtypes of tumor, the matricellular protein osteopontin (OPN, Spp-1) was the only small molecule that differed in concentration between WHFs from luminal and TN breast cancer." (PMID 30791501, 2019). "Both JUN and SPP1 are genes known to promote cancer cell invasiveness and tumor metastasis." (PMID 30459815, 2018). "The expression levels of these cytokines were assessed in 4T1 tumours, which revealed a striking similarity to the reparative tissue response, including significantly higher Spp1, Il1b, Csf3, Il6 and Osm expression in 4T1 tumours compared to healthy mammary fat pad tissue." (PMID 30054470, 2018). "Both Jun and SPP1 are known molecules involved in cancer cell invasiveness and tumor metastasis." (PMID 30459815, 2018). "Up-regulation of the SPP1, miR-122, SRPX2, ADH1B, miR-21, SALL4 and PRAP1 genes, as well as down-regulation of miR-378e have been previously associated with an increased tumor cell migration capacity among sCRC, greater tumor progression potential, a metastatic phenotype and inhibition of apoptosis." (PMID 29296198, 2017). "In the present study we show the important role of tumour-derived SPP1 in stemness maintenance." (PMID 28030801, 2017). "Previous studies have determined the expression of SPP1-a,-b,-c isoforms in tumour tissues." (PMID 28030801, 2017). "We further examined whether blocking FN1/SPP1-ITGAV signaling could inhibit the outgrowth of tumor cells in fibrotic lungs." (PMID 27329720, 2016). "Both control and SPP1 knockdown cell lines formed tumour colonies in soft agar." (PMID 25884485, 2015). "The expression level of SPP1 was also dependent on tumor grade." (PMID 25658639, 2015). "shRNA knockdown of four different MPNST cell lines revealed a significant reduction in tumour colony size growth, wound healing and cell invasion, thereby supporting a role for the increased expression of SPP1 in the malignant transformation and invasion of cells during NF1-MPNST development." (PMID 25884485, 2015). "Comparing the osteogenic potential between these cell lines, LNCaP-19 exclusively has a basal expression of osteoblast-cadherin (CDH11), collagen 1a1 (COL1A1) and osteopontin (Opn, SPP1), all vital genes for tumor interaction with osteoblasts and osteoblastic activity." (PMID 24292404, 2014). "Tumour oncogenes include SPP-1, MITF, CITED-1, GDF-15, c-Met, and HOX loci." (PMID 23091727, 2012). "Spp1 is also a known enhancer of tumor development and metastasis." (PMID 22281153, 2012). "We also identified a large number of cell adhesion and cell communication pathway genes, such as CDH3, SPP1, SPINK and CEACAM5 that are highly up-regulated in all lung AC tumours, and hence could be associated with the early metastasis of lung AC." (PMID 22369099, 2011). "Neither SPP1 overexpression nor tumor grade was significantly associated with survival in either analysis." (PMID 21383983, 2011). "During promotion, the majority of genes identified in the BALBLps-d compared to BALB/c mice (P < 0.05) were involved in epithelial growth factor receptor (EGFR) signaling (e.g. epiregulin (Ereg)), secreted phosphoprotein 1(Spp1)), which can lead to cell growth and eventual tumor development." (PMID 19925653, 2009). "In addition, there was a significantly greater level of SPP1 in biopsy samples than in both primary tumor resections and metastatic samples (p = 0.002, p = 0.0002, respectively)." (PMID 17022822, 2006). "Additionally, the SPP1 gene characterizes macrophage subsets that contribute to tumor promotion." (PMID 41429574, 2026). "The SPP1/C1QC signatures could effectively predict tumor stages and clinical outcomes." (PMID 41341850, 2025).
tumor (continued). "Myeloid cells infiltrated in the tumor tissues were sub-clustered into seven phenotypes, including monocyte, myeloid-derived suppressor cells (MDSCs), M1 macrophages, M2 macrophages, macrophages expressing Spp1 (Spp1_macrophage), proliferative_macrophages, and Osteoclast-like cells." (PMID 40186298, 2025). "These activated SPP1+ macrophages, in turn, neutralize T-cell function by secreting immunosuppressive cytokines and promoting the expansion of regulatory T cells (Tregs), while also facilitating tumor growth and metastasis by promoting angiogenesis and extracellular matrix (ECM) remodeling." (PMID 41374989, 2025). "Compared to other subsets, SPP1+ TAMs are extensively increased in tumor tissues and are more likely to be enriched in the tumor core, suggesting that they may play a key role in promoting tumor growth." (PMID 40230843, 2025). "Notably, a recent milestone study using single-cell sequencing analysis found that SPP1 expression patterns follow hierarchical relationships of tumor cell branching evolution, positioning SPP1 as a candidate regulator of tumor evolution in response to treatment." (PMID 40901047, 2025). "Additionally, the characteristic expression profile of this cell subgroup included multiple myeloid cell activation markers, such as IL1RN, CXCL8, CCL20, and the chemokines CCL3 and SPP1, indicating the activated state of myeloid cells in the tumour microenvironment." (PMID 40539065, 2025). "Additionally, undifferentiated HLA-G+ tumor cells may contribute to the polarization of macrophages to an SPP1+ phenotype, further inducing an immunosuppressive TME." (PMID 41316282, 2025). "Additionally, SPP1 recruits immunosuppressive myeloid cells, further promoting tumor progression." (PMID 40076844, 2025). "Recognizing the critical role of ECM in tumor progression through dynamic remodeling, and identifying cancer-associated fibroblasts (CAFs) as key cellular components in ECM remodeling, we hypothesized that SPP1+ TAMs may synergize with CAFs to facilitate tumor progression." (PMID 40230843, 2025). "Notably, PLXDC1+TPSCs located near aggressive LRRC15+ myCAFs and SPP1+ macrophages could form a desmoplastic and immunosuppressive niche around the tumor boundary, promoting CD8 T cell exhaustion in pancreatic ductal adenoma." (PMID 41425545, 2025). "Compared to IMs, recMacs were enriched for canonical tumor-promoting transcripts including Spp1, Vegfa, Arg1, and Cd274 Together, these data suggest that while both populations contribute to immune regulation, recMacs are more transcriptionally aligned with tumor-promoting programs." (PMID 40630529, 2025). "Additionally, within the tumor microenvironment, two distinct tumor-associated macrophage (TAM) clusters were enriched in PitNETs, one with pro-inflammatory M1 features and the other with immunosuppressive M2 marker upregulation (SPP1, TREM2, and CX3CR1)." (PMID 40959438, 2025). "Additionally, reprogramming SPP1+TAMs into CXCL9+ TAMs may offer an alternative approach to enhance anti-tumor immunity and reshape the immune landscape in HCC." (PMID 40230843, 2025). "Another study revealed that SPP1+ macrophages—particularly the subset expressing signal regulatory protein α (SIRPα)—exhibit high PD-L1 expression across multiple tumor types, suggesting that these macrophages may contribute to immune regulation through PD-L1/PD-1 interactions." (PMID 41391064, 2025). "Targeting SPP1+ macrophages may be a possible strategy for anti-tumor growth and metastasis." (PMID 38307957, 2024). "Therefore, we hypothesized that regulating IGF1, CDKN2A, BIRC5, and SPP1 levels may affect the tumor immune microenvironment in HCC." (PMID 39042294, 2024). "Additionally, we identify potential interacting proteins and enriched pathways that may mediate the tumor-promoting effects of SPP1." (PMID 39727934, 2024).